IL2 (interleukin 2)
Diseases named in the same sentence as IL2 in open-access papers (continued):
Sharing a sentence is not in itself a finding about the gene and the disease.
metastatic melanoma (continued). "In addition to IL-2 (approved for metastatic kidney cancer and metastatic melanoma in 1992 and 1998), IFN-α has been approved by the USFDA for the treatment with hairy cell leukemia (1986), and TNF (tasonermin) was licensed in Europe for irresectable soft tissue sarcoma in the 1999." (PMID 33717106, 2021). "L19-IL2 is an immunocytokine featuring the L19 antibody fused to the cytokine IL2 payload, which is currently being investigated with encouraging results for the treatment of metastatic melanoma in phase II and phase III clinical trials, in combination with targeted TNF." (PMID 33110477, 2020). "For instance, high dose IL-2 is part of the protocol for adoptive TIL therapy against metastatic melanoma, despite actively expanding immunosuppressive ICOS+ Treg cells, supporting the possibility that high-dose IL-2 is successful because it may render TIL resistant to Treg cell suppression." (PMID 31058083, 2019). "Immune activating agents including interleukin-2 (HD IL-2), anti-Cytotoxic T-lymphocyte associated protein (CTLA-4), programmed cell death (PD-1) and programmed death-ligand 1 (PD-L1) antagonists are the most active treatments for many patients with metastatic melanoma." (PMID 25806109, 2015). "In a subsequent study, same authors hypothesized that in patients with metastatic melanoma, CTLA-4 blockade might enhance the antitumor effect of IL-2, since IL-2 stimulates T-cell growth, but has also been implicated in the expansion of Tregs that express cell-surface CTLA-4." (PMID 24594636, 2014). "Similarly, a phase III metastatic melanoma trial, which compared peptide vaccination in combination with IL-2 therapy to IL-2 therapy alone, showed a significant improvement in overall response rate and progression-free survival in those patients who had received the vaccine." (PMID 23606870, 2013). "Also renal cell carcinomas are as sensitive to systemic administration of IL-2 as metastatic melanoma yet, while in the latter adaptive immune responses are easily demonstrable, in the former, they have been quite elusive, and most likely of secondary significance." (PMID 19583830, 2009). "Before 2010, only dacarbazine chemotherapy and high-dose interleukin-2 (IL-2) were approved by the U.S. Food and Drug Administration (FDA) for the treatment of metastatic melanoma." (PMID 40098976, 2025). "Aldesleukin is a recombinant IL‐2, which has been approved by the FDA for the treatment of metastatic melanoma." (PMID 40243372, 2025). "Interleukin-2 (IL-2) and interferon-alpha (IFN-α) were among the first cytokines used in oncology, showing clinical benefit in subsets of patients with metastatic melanoma and RCC by enhancing cytotoxic immune activity." (PMID 40950404, 2025). "Since its discovery in 1976 and the subsequent understanding of its vital role as a lymphocyte T-cell growth factor, the cytokine IL-2 was approved in the 1990s for use in patients with advanced-stage cancer, including RCC and later for metastatic melanoma." (PMID 39852848, 2025). "This case is the first to demonstrate the successful treatment of a metastatic melanoma patient with concurrent CLL/SLL using lymphodepleting chemotherapy followed by unselected TIL and interleukin-2." (PMID 41333460, 2025). "The first cytokine therapy, interleukin-2 (IL-2, aldesleukin), was approved by the U.S. FDA in 1992 for the treatment of metastatic renal cellcarcinoma and later in 1998 for metastatic melanoma." (PMID 41568361, 2025). "Similar result was found in metastatic melanoma patients; those with elevated serum LDH level showed a low NK cell activity and NK cell receptor expression upon stimuli of IL-2, IL-12, and their combination." (PMID 39286242, 2024). "IL-2 received FDA approval for treating metastatic renal cell carcinoma in 1992 and metastatic melanoma in 199336." (PMID 39617785, 2024).
metastatic melanoma (continued). "Patients with refractory metastatic melanoma and synovial cell sarcoma with NY-ESO-1-positive tumors received antigen-specific TCR-transduced T-cells, along with IL-2 following chemotherapy." (PMID 39337333, 2024). "Studies have shown that refractory metastatic melanoma patients that receive cell infusion with autologous tumor-reactive, rapidly expanded TIL cultures, and high-dose Interleukin-2 (IL-2) therapy have improved outcomes." (PMID 38915379, 2024). "In the 1990s, IL-2 received approval from the US Food and Drug Administration (FDA) for the treatment of metastatic renal cell carcinoma and metastatic melanoma." (PMID 38554155, 2024). "In this case series, we describe the use of intralesional IL-2 and BCG at our institution in ten patients with in-transit plus or minus distant cutaneous metastatic melanoma over the last twelve years." (PMID 37182189, 2023). "For example, high-dose IL-2, combined with ipilimumab (an anti-CTLA-4 antibody), has shown promise by inducing durable responses in patients with metastatic melanoma." (PMID 37516849, 2023). "IL-2 is one of the most effective FDA-approved agents in the treatment of metastatic renal cell carcinoma and metastatic melanoma." (PMID 36631633, 2023). "Previous therapy directed at LMD and/or metastatic melanoma is allowed, including IT therapy (washout 7 d), radiation (washout 7 d) and systemic biologic therapy (CTLA4 and/or PD, IL-2, interferon, washout 14 d)." (PMID 36997799, 2023). "High-dose IL-2 (HDIL-2) was approved by the FDA for the treatment of metastatic renal cell carcinoma in 1992 and of metastatic melanoma in 1998." (PMID 37711172, 2023). "Subsequently, high-dose IL-2 therapy was authorized by the FDA in 1992 and 1998 for the treatment of metastatic renal cell carcinoma (RCC) and metastatic melanoma, respectively." (PMID 37483629, 2023). "High-dose IL-2 has shown anti-tumor activity in patients with metastatic melanoma but with high rate of serious adverse events; BEMPEG was engineered to increase the half-life of IL-2 allowing for less frequent dosing and a more favorable safety profile." (PMID 37507765, 2023). "Interleukin-2 (IL-2), also known as aldesleukin or PROLEUKIN®, is considered to be an immunotherapy treatment for people with metastatic melanoma." (PMID 38001643, 2023). "High-dose IL-2 therapy was approved by the FDA for the treatment of metastatic renal cell carcinoma in 1992 and for metastatic melanoma in 1998." (PMID 37174716, 2023). "In the 1990s, interleukin-2 (IL-2) earned FDA-approval after achieving complete responses in a small subset of patients with metastatic renal cell carcinoma and metastatic melanoma." (PMID 36712341, 2022). "For example, IL-2 is the only drug approved in the United States for the treatment of metastatic Renal cell carcinoma (RCC) and metastatic melanoma." (PMID 35155574, 2022). "Combination of high‐dose IL‐2 with PD‐1/PD‐L1 blockade therapy displays an objective response rate (ORR) of 22.5% and 24% for metastatic melanoma and metastatic renal cell carcinoma (RCC), respectively." (PMID 35301813, 2022). "High-dose (HD) IL-2 was approved by the FDA for the treatment of metastatic renal cell carcinoma in 1992 and metastatic melanoma in 1998." (PMID 35213635, 2022). "Recombinant human high-dose IL2 (HD-IL2; aldesleukin) was one of the first approved immune-oncology agents based upon clinical activity in renal cell carcinoma (RCC) and metastatic melanoma but use was limited due to severe toxicity." (PMID 36923304, 2022). "Recombinant IL-2 has been used successfully for cancer therapy and was approved by the FDA for the treatment of metastatic renal-cell carcinoma in 1992 and for metastatic melanoma in 1998." (PMID 35177742, 2022).
metastatic melanoma (continued). "Due to its immunostimulatory activity, high-dose IL-2 was tested in patients with cancer and became the first cytokine approved by the FDA for the treatment of metastatic renal cell carcinoma and metastatic melanoma in 1992 and 1998, respectively." (PMID 35651800, 2022). "IL-2 is approved for treatment of advanced renal cell carcinoma (RCC) and metastatic melanoma.IFN-α is approved for treatment of follicular lymphoma, hairy cell leukemia, AIDS-related Kaposi’s sarcoma, and melanoma." (PMID 35529882, 2022). "For example, the combined delivery of a TGF-β antagonist and IL-2 by nanoscale liposomal polymeric gels substantially enhanced activated CD8+ T-cell infiltration in tumors and improved the survival of metastatic melanoma-bearing mice." (PMID 34419164, 2021). "The N-(4-18F-fluorobenzoyl)-interleukin-2 (18F-FB-IL2), which is currently used in a clinical trial in metastatic melanoma at the University Medical Center, Groningen." (PMID 34298967, 2021). "Historically, there were only dacarbazine chemotherapy and high-dose interleukin-2 (IL-2) approved by Food and Drug Administration (FDA) as treatment agents for metastatic melanoma before 2010." (PMID 34924562, 2021). "As a result, high-dose IL-2 therapy received FDA approval in 1992 for metastatic RCC and 1998 for metastatic melanoma." (PMID 34790830, 2021). "One promising immunotherapy is recombinant interleukin-2 (IL2) which expands antigen-specific CD8 T cell populations, and it has been shown to induce durable disease control in some patients with metastatic melanoma and renal cell carcinoma." (PMID 33937052, 2021). "Subsequently, recombinant interleukin-2 (IL-2) was approved by the FDA as a cancer immunotherapy drug for the treatment of metastatic renal cancer (in 1992) and metastatic melanoma (in 1998), separately." (PMID 32123302, 2020). "Interleukin-2 (IL-2) is a T-cell growth factor, which became one of the first FDA-approved immunotherapeutic agents for the treatment of metastatic melanoma and renal cell cancer." (PMID 32917054, 2020). "High-dose (HD) recombinant IL2 therapy has been shown to be effective and has been approved by the Food and Drug Administration (FDA) for the treatment of renal cell carcinoma and metastatic melanoma." (PMID 32560387, 2020). "Despite its low safety profile, IL-2 became an FDA-approved drug (Proleukin, Novartis; generic name Aldesleukin) for renal cell carcinoma and metastatic melanoma treatment." (PMID 32917054, 2020). "In the case of IL-2, which has been approved by FDA for the treatment of advanced renal cell carcinoma and metastatic melanoma." (PMID 32610601, 2020). "So far, the only FDA approved agents for treatment of metastatic melanoma are cytostatic DTIC and immunotherapeutic Interleukin-2 (IL-2), ipilimumab, an anti-CTLA4-antibody and nivolumab, which blocks the programmed cell death protein 1 (PD-1) of T-cells." (PMID 30682171, 2019). "When combined with interleukin-2 (IL-2) and lymphodepletion, ACT has led to complete and durable tumor regression in up to 20% of patients with metastatic melanoma." (PMID 29843822, 2018). "In metastatic melanoma, for example, the cooperation of CD8+ T cells and Natural Killer cells are necessary to mediate anti-tumor activity during combination therapy with IL2 and anti-CTLA, and for the use of BRAF inhibitors in metastatic melanoma." (PMID 27377892, 2016). "Here, we measured the extent of HD IL-2-induced phosphorylation of STAT5 and STAT1 in lymphocyte subsets from metastatic melanoma patients and healthy controls at a single cell level using flow cytometry." (PMID 27153543, 2016). "Despite several new options in the treatment of metastatic melanoma and RCC, HD IL2 continues to be widely used as salvage therapy." (PMID 26799322, 2016). "In our two patients with metastatic melanoma who had received an ASCT remotely, one received high dose IL-2 alone, and the other high dose IL-2, ipilimumab, and anti-PD1 therapy sequentially." (PMID 25806109, 2015).
metastatic melanoma (continued). "We report the consequences of administering HD IL-2, ipilimumab, and anti-PD1 therapy sequentially to one patient with metastatic melanoma occurring remotely following ASCT, and HD IL-2 alone to a second patient." (PMID 25806109, 2015). "For more than 2 decades, dacarbazine and interleukin-2 (IL-2) were the only agents approved by the US Food and Drug Administration (FDA) for the treatment of advanced or metastatic melanoma." (PMID 26328215, 2014). "The antitumor activity of recombinant IL-2 in preclinical and clinical settings) led to 7 pivotal clinical trials and FDA approval for patients with metastatic kidney cancer in 1992 and metastatic melanoma in 1998." (PMID 24855563, 2014). "IL-2 has, for instance, been approved by the US Food and Drug Administration (FDA) for the treatment of metastatic melanoma and renal-cell carcinoma." (PMID 24860566, 2014). "IL-2, a T-cell growth factor, has been approved by the FDA for the treatment of patients with metastatic melanoma and renal cell carcinoma." (PMID 22778760, 2012). "Also, we have initiated a new trial for metastatic melanoma patients using young-TIL ACT in combination with intermediate doses of IL-2 (ClinicalTrials.gov ID: NCT00937625) with the purpose of defining the most optimal dose of IL-2 for the use in a larger randomized clinical trial." (PMID 22909342, 2012). "So far, only two drugs have been approved by the Food and Drug Administration (FDA) for the treatment of metastatic melanoma patients, the chemotherapeutic agent dacarbazine (DTIC) and the immunomodulator Interleukin-2 (IL-2)." (PMID 21234353, 2010). "Interleukin-2 (IL2) is one of the three drugs currently approved by the U.S. Food and Drug Administration (FDA) for the treatment of metastatic melanoma." (PMID 19640287, 2009). "All patients had failed previous therapy with conventional treatments for metastatic melanoma (IFN, high dose IL-2, biochemotherapy, or chemotherapy)." (PMID 19270751, 2009). "We have examined the efficacy, toxicity and host immunological response of two different dose schedules of interleukin 2 (IL-2) given subcutaneously, daily for 3 months in patients with renal cell carcinoma (RCC) or metastatic melanoma (MM)." (PMID 8855983, 1996). "Natural killer (NK) cell activity and lymphokine activated killer (LAK) cell cytotoxicity were measured in patients receiving recombinant interleukin 2 (rIL-2) and flavone acetic acid (FAA) for treatment of progressing metastatic melanoma." (PMID 2328217, 1990). "Recombinant interleukin 2 (rIL-2) and flavone acetic acid (FAA) were used to treat 34 patients with progressing metastatic melanoma." (PMID 2331447, 1990). "IL-2 is a key cytokine involved in immune system homeostasis and T-cell maintenance and was previously approved by the FDA as immunotherapy for metastatic renal cell carcinoma and metastatic melanoma." (PMID 39984775, 2025). "The immunocytokine (IC) IL-2, i.e., L19-IL2, in which IL-2 was fused to a humanized mAb L19, was capable of specific accumulation in tumor neovasculature, showing encouraging results in patients with metastatic melanoma." (PMID 39415291, 2024). "To date, IL-2 has been approved by the FDA as a treatment for advanced renal cell carcinoma and metastatic melanoma, and IFN-α has been approved as a treatment for hairy cell leukemia, follicular non-Hodgkin lymphoma, melanoma and AIDS-related Kaposi’s sarcoma." (PMID 39617785, 2024). "Interleukin-2 (IL-2), a potent T-cell-stimulating cytokine, was the first U.S. Food and Drug Administration (FDA)-approved immunotherapeutic with considerable treatment effects in metastatic melanoma and renal cell carcinoma (RCC) patients." (PMID 39218982, 2024).
metastatic melanoma (continued). "In particular, Raphael and Kuttan demonstrated that administration of glycyrrhizic acid clearly enhanced the level of interleukin IL-2, the antibody-dependent cell mediated cytotoxicity (ADCC) and antibody-dependent complement-mediated cytotoxicity (ACC) in B16-F10 metastatic melanoma-bearing mice." (PMID 36768978, 2023). "High dose IL-2 is approved by the FDA for treatment of metastatic RCC and metastatic melanoma." (PMID 35529882, 2022). "Interleukin 2 (IL-2) is another cytokine that demonstrated efficacy and was approved by the Food and Drug Administration (FDA) for metastatic renal cell cancer in 1992 and metastatic melanoma in 1998." (PMID 35936003, 2022). "More recently, a meta-analysis identified 13 studies of TIL therapy and IL-2 following non-myeloablative chemotherapy in metastatic melanoma patients." (PMID 35538491, 2022). "The survival rate was statistically higher in the context of developing irAEs during or after IL-2 therapy, with a mean of 48 months in patients with metastatic melanoma versus 18 months in those who did not develop irAEs." (PMID 36556267, 2022). "The ability of IL-2 to mediate tumor regression in preclinical and clinical settings led to FDA approval for its use in the treatment of metastatic renal cell carcinoma and metastatic melanoma in the 1990s." (PMID 34790830, 2021). "Adoptive cell transfer that uses TILs (ACT-TIL) was first successfully observed in 60% of metastatic melanoma patients who had not been treated with interleukin-2 (IL-2) and 40% of non-respondents IL-2 treatments which resulted in cancer regression." (PMID 33042104, 2020). "A 54-year-old Caucasian male with metastatic melanoma (diagnosed prior to the era of B-Raf inhibitors) initially received interleukin-2 without benefit followed by right hepatic lobectomy." (PMID 31703593, 2019). "Our small molecule, Compound A, was also identified as a potent immunomodulator that is able to induce cytokine production (IL-2 and IFN-γ) and T cell proliferation, at levels comparable to pembrolizumab – an approved anti-PD-1 human mAb for treating metastatic melanoma." (PMID 31455818, 2019). "In addition to IL-2, combinations of vemurafenib with IFN α-2b or peg-IFN were tested in patients with metastatic melanoma (NCT01943422, NCT01959633)." (PMID 31134073, 2019). "Aldesleukin, a recombinant form of IL-2, is the first approved immuno-oncology drug leading to complete, durable remissions in metastatic melanoma and renal cell carcinoma patients." (PMID 30400822, 2018). "We conducted a pilot study in patients with metastatic melanoma receiving ipilimumab (IPI) or pembrolizumab (PEMBRO) to assess safety and feasibility of SPECT/CT imaging with 99mTc- interleukin-2 (99mTc-HYNIC-IL2) to detect TILs and distinguish between true progression from pseudo- progression." (PMID 30100988, 2018). "In 1998, interleukin-2 (IL-2), a T-cell growth factor that aids in immune regulation and T-cell proliferation, became the second antitumor cytokine approved by the FDA when it was approved in the treatment of metastatic melanoma and renal cell carcinoma." (PMID 30333937, 2017). "The PROCLAIM database was queried for patients with metastatic melanoma who had received HD IL-2 after treatment with ipilimumab or without prior ICB." (PMID 27660706, 2016). "Indeed, a high serum level of sIL-2Rα in patients with metastatic melanoma is strongly correlated with poor outcomes from anti-CTLA-4 treatment, which requires concomitant IL-2-mediated immune activation." (PMID 27876012, 2016). "In patients with advanced metastatic melanoma, a non-myeloablative regimen prior to infusion of tumor-infiltrating lymphocytes and bolus IL-2 resulted in an objective response rate of 50 %." (PMID 26885368, 2016). "A total of 52 metastatic melanoma patients were treated with high dose IL-2 after ipilimumab and 276 patients were treated with high dose IL-2 without prior ICB." (PMID 27660706, 2016).